XRCC5 (X-ray repair cross complementing 5)
Description:
DNA-binding protein critical for the DNA damage response, specifically in repairing double-strand breaks (DSBs) via the classical non-homologous end joining (NHEJ) pathway. It forms a heterodimer with XRCC6 (Ku70), creating the Ku70:Ku80 heterodimer (Ku complex), which serves as a DNA end-binding complex. It primarily binds DSBs and recruits essential repair factors, assembling the core long-range NHEJ complex to facilitate the alignment and ligation of broken DNA ends. This pathway ensures the rapid repair of cytotoxic and mutagenic DSBs and contributes to the generation of diversity in T-cell receptors and antibodies through mechanisms such as V(D)J recombination. Likely acts as a 5'-deoxyribose-5-phosphate lyase (5'-dRP lyase), catalyzing the beta-elimination of the 5'-deoxyribose-5-phosphate at abasic sites near DSBs. This activity cleans the termini of abasic sites, a common form of nucleotide damage, preparing broken ends for ligation. It may also possess 3'-5' DNA helicase activity, although this has not been confirmed in vivo, and its physiological significance remains unclear. Beyond DNA repair, the protein contributes to telomere maintenance. It is also implicated in transcriptional regulation, acting as a cofactor for various transcription factors. It plays a role in the regulation of DNA virus-mediated innate immune response by assembling into the HDP-RNP complex, a complex that serves as a platform for IRF3 phosphorylation and subsequent innate immune response activation through the cGAS-STING pathway. Can also bind RNAs and recruits PRKDC to a wide range of cellular RNAs, including the U3 small nucleolar RNA, playing a role in the biogenesis of ribosomal RNAs.
Synonyms: KU80; KARP-1; Ku86; KUB2; KARP1; NFIV
Tractability: Small molecule: a structure with a bound ligand is known. Antibody: its Gene Ontology location is reachable by antibodies, with high confidence. PROTAC: UniProt records ubiquitination sites on it; ubiquitination databases record sites on it; its protein half-life has been measured; a small molecule that binds it is known.
Target class: Enzyme; Hydrolase
Gene: Protein-coding gene on chromosome 2 (216,107,464 to 216,206,303, forward strand). Ensembl gene ENSG00000079246.
Subcellular location: Nucleus; Nucleus, nucleolus; Chromosome
Subcellular location (Human Protein Atlas): Nucleoplasm
Pathways (Reactome):
Immune System: Cytosolic sensors of pathogen-associated DNA; IRF3-mediated induction of type I IFN; Neutrophil degranulation
DNA Repair: Nonhomologous End-Joining (NHEJ)
Disease: 2-LTR circle formation
Gene Ontology:
Molecular function: 5'-deoxyribose-5-phosphate lyase activity; ATP hydrolysis activity; ATP-dependent activity, acting on DNA; class I DNA-(apurinic or apyrimidinic site) endonuclease activity; DNA end binding; double-stranded telomeric DNA binding; protein binding; protein-containing complex binding; RNA binding; telomeric DNA binding; transcription cis-regulatory region binding; U3 snoRNA binding; ubiquitin protein ligase binding; DNA binding; DNA helicase activity; double-stranded DNA binding; enzyme activator activity; 3'-5' DNA helicase activity; damaged DNA binding
Biological process: activation of innate immune response; cellular response to gamma radiation; DNA damage response; double-strand break repair; double-strand break repair via nonhomologous end joining; negative regulation of DNA-templated transcription; negative regulation of t-circle formation; protein localization to chromosome, telomeric region; regulation of smooth muscle cell proliferation; small-subunit processome assembly; telomere maintenance via telomerase; DNA recombination; recombinational repair; regulation of telomere maintenance; telomere maintenance
Cellular component: chromosome; chromosome, telomeric region; DNA-dependent protein kinase complex; DNA-dependent protein kinase-DNA ligase 4 complex; Ku70:Ku80 complex; membrane; nonhomologous end joining complex; nucleolus; nucleoplasm; nucleus; protein-containing complex; protein-DNA complex; ribonucleoprotein complex; site of DNA damage; small-subunit processome; cytosol; extracellular region; nuclear telomere cap complex; secretory granule lumen; cytoplasm
Genetic constraint (gnomAD): Loss-of-function variants: 9 observed, 81.31 expected, observed/expected ratio (o/e) 0.11, 90% interval 0.066 to 0.19. The upper end of that interval is the gene's LOEUF score, 0.19, which puts it in group 1 of 6, group 1 being the genes least tolerant of losing a copy. Missense variants: 546 observed, 842.94 expected, observed/expected ratio (o/e) 0.65, 90% interval 0.6 to 0.69. Synonymous variants: 267 observed, 280.03 expected, observed/expected ratio (o/e) 0.95, 90% interval 0.86 to 1.05.
Homologues: Orthologues: chimpanzee XRCC5 (99% identical), macaque XRCC5 (99% identical), rabbit XRCC5 (85% identical), guinea pig XRCC5 (83% identical), pig XRCC5 (83% identical), dog XRCC5 (83% identical), mouse Xrcc5 (78% identical), rat Xrcc5 (78% identical), tropical clawed frog tmem169 (63% identical), zebrafish xrcc5 (56% identical), Drosophila melanogaster Ku80 (22% identical), Caenorhabditis elegans cku-80 (20% identical). Paralogues in human: XRCC6 (14% identical).
Diseases named in the same sentence as XRCC5 in open-access papers:
XRCC5 is named in the same sentence as 120 diseases in open-access papers, as found by Europe PMC text mining. Sharing a sentence is not in itself a finding about the gene and the disease. The quoted sentences say what the papers report.
breast cancer (34 papers, 2009 to 2025). A primary or metastatic malignant neoplasm involving the breast. "The present study aimed to clarify the effects of XRCC5/6 polymorphisms on breast cancer susceptibility among Chinese women and their potential interactions with smoking, alcohol consumption, and sleep satisfaction." (PMID 33734613, 2021). "This study aimed to determine the influence of XRCC5/6 polymorphisms on breast cancer risk, and their interactions with cigarette smoking, alcohol consumption, and sleep satisfaction." (PMID 33734613, 2021). "Increased ER+/PR+ breast cancer risk in the co‐dominant genetic model of XRCC5 rs16855458 after Bonferroni correction was observed (ptrend = 0.008)." (PMID 33734613, 2021). "XRCC5 rs16855458 was associated with increased breast cancer risk in the co‐dominant (ptrend = 0.003) and dominant (CA + AA vs. CC, OR = 1.29, 95% CI = 1.07–1.56, p = 0.008) genetic models after Bonferroni correction." (PMID 33734613, 2021). "The present study revealed increased ER+/PR+ breast cancer risk in the co‐dominant genetic model of XRCC5 rs16855458." (PMID 33734613, 2021). "Herein, an antagonistic interaction was identified between the XRCC5 rs16855458 CA + AA genotype and alcohol consumption in breast cancer risk." (PMID 33734613, 2021). "A strong correlation was found between the variable number tandem repeat polymorphism in the XRCC5 gene and the risk of breast cancer." (PMID 33006365, 2020). "As the regulatory subunit of the DNA-dependent protein kinase complex DNA-PK, XRCC5 is associated with the development of tumors such as lung cancer, breast cancer, and bladder cancer." (PMID 30217218, 2018). "The frequently observed VNTR association with in BRCA1+ and BRCA2+ breast cancer group indicates that VNTR polymorphism in the XRCC5 promoter is associated with altered risk of breast cancer in BRCA1+ and BRCA2+ carriers." (PMID 27148484, 2016). "Our study provides evidence showing that VNTR polymorphisms in the XRCC5 promoter is associated with risk of familial breast cancer with BRCA1+ and BRCA2+ predisposition." (PMID 27148484, 2016). "VNTR polymorphisms in the XRCC5 promoter are associated with sporadic bladder, gastric, and breast cancer." (PMID 27148484, 2016). "The different results suggest that the association of VNTR polymorphisms in the XRCC5 promoter differs between familial breast cancer and sporadic breast cancer." (PMID 27148484, 2016). "Association of VNTR genotypes in XRCC5 promoter with familial breast cancer-affected and -unaffected groups." (PMID 27148484, 2016). "Logistic regression analyses showed that XRCC5 rs16855458 was associated with increased breast cancer risk in the co‐dominant genetic model (ptrend = 0.003), and the dominant genetic model (CA + AA vs. CC: OR = 1.29, 95% CI = 1.07–1.56, p = 0.008) after the Bonferroni correction." (PMID 33734613, 2021). "However, the AA genotype of XRCC5 rs16855458 was associated with an increased risk of both ER+/PR+ and ER−/PR− breast cancer." (PMID 33734613, 2021). "Breast cancer risk associated with XRCC5 and XRCC6 polymorphisms might vary according to alcohol consumption and sleep satisfaction, respectively, and merit further investigation." (PMID 33734613, 2021). "Therefore, the relationship between XRCC5 rs16855458 and breast cancer risk by different hormone receptor states needs to be further explored." (PMID 33734613, 2021). "The data revealed that XRCC5 rs16855458 was associated with increased breast cancer risk in the co‐dominant genetic model, and the CG + GG genotype of XRCC6 rs2267437 was associated with an increased risk of ER−/PR− breast cancer, even after Bonferroni correction." (PMID 33734613, 2021). "XRCC5 rs16855458 and rs9288516 have potential biological functions as they cause changes in the binding sites of transcription factors, and correlate with risk for hepatocellular carcinoma, whereas XRCC6 rs2267437 and XRCC5 rs3835 were correlated with breast cancer risk in European women." (PMID 33734613, 2021).
breast cancer (continued). "However, relatively few studies have investigated XRCC5/6 polymorphisms and breast cancer susceptibility in Chinese women, and available results have been inconsistent." (PMID 33734613, 2021). "The present study showed that XRCC5 rs16855458 polymorphism correlates with breast cancer risk." (PMID 33734613, 2021). "The AA genotype of XRCC5 rs16855458 was associated with an increased risk of both ER+/PR+ and ER−/PR− breast cancer (AA vs. CC: for ER+/PR+, OR = 1.84, 95% CI = 1.10–3.07, p = 0.019; for ER−/PR−, OR = 2.25, 95% CI = 1.14–4.46, p = 0.019), but not after Bonferroni correction." (PMID 33734613, 2021). "Using PCR, PAGE, Sanger sequencing, and statistical analyses, we compared VNTR genotypes in the XRCC5 promoter between healthy individuals and three types of familial breast cancer cases: mutated BRCA1 (BRCA1+), mutated BRCA2 (BRCA2+), and wild-type BRCA1/BRCA2 (BRCAx)." (PMID 27148484, 2016). "Therefore, we screened germline VNTR polymorphisms in the XRCC5 promoter in three types of familial breast cancer (BRCA1+, BRCA2+, and BRCAx)." (PMID 27148484, 2016). "In breast cancer, there are NHEJ genes XRCC5/Ku80 and XRCC6/Ku70 polymorphisms associated with breast cancer risk and chromosomal radiosensitivity." (PMID 39334297, 2024). "Recently, XRCC5 has been reported to be highly expressed in various tumors such as gastric cancer, breast cancer and hepatocellular carcinoma 35-37." (PMID 33403043, 2021). "The effects of potential interactions between target (XRCC5 and XRCC6) SNPs and smoking, alcohol consumption, and sleep satisfaction on breast cancer risk were analyzed." (PMID 33734613, 2021). "XRCC5 rs16855458 was associated with breast cancer risk, and XRCC6 rs2267437 was associated with the risk of ER−/PR− breast cancer." (PMID 33734613, 2021). "This study aimed to determine the influence of XRCC5 and XRCC6 polymorphisms on breast cancer risk, and potential interactions with cigarette smoking, alcohol consumption, and sleep satisfaction." (PMID 33734613, 2021). "This study provides new evidence that XRCC5 rs16855458 is associated with breast cancer risk among Chinese women, and that XRCC6 rs2267437 is associated with the risk of ER−/PR− breast cancer." (PMID 33734613, 2021). "Antagonistic interaction between XRCC5 rs16855458 and alcohol consumption, and synergistic interaction between XRCC6 rs2267437 and sleep satisfaction were also found to affect breast cancer risk." (PMID 33734613, 2021). "MiR-623 significantly suppressed XRCC5 expression, which is critical for miR-623-induced proliferation and migration block in breast cancer cells." (PMID 32501811, 2020). "The predicted direction of association with contralateral breast cancer risk was uniformly increased for the LIG4, NHEJ1, and XRCC5 genes while uniformly decreased for the XRCC4 and XRCC6 genes." (PMID 31560388, 2019). "We compared the VNTR genotype distributions in the XRCC5 promoter between three types of familial breast cancer: BRCA1+, BRCA2+, and BRCAx." (PMID 27148484, 2016). "A decrease in the transcription levels of human invasion signature (HIS) genes (ARHGDIB, CAPZA2, PHACTR2, CDC42, XRCC5, and CAV1) has been also demonstrated by real-time PCR, with high expression of these genes being a hallmark of actively metastasizing breast cancer cells." (PMID 36143471, 2022). "In previous studies, it was reported that XRCC5 promotes cancer cell growth (colon cancer and breast cancer), and the inhibition of XRCC5 using siRNA have been show to suppress cancer cell growth in vitro and, conversely, the overexpression of XRCC5 promoted cancer cell growth." (PMID 34750284, 2022). "Due to the lack of complete human epidermal growth factor receptor 2 (HER2) status data, this study only analyzed the correlation between XRCC5/6 polymorphisms and the risk of breast cancer by different hormone receptor states, but not molecular subtypes." (PMID 33734613, 2021).
breast cancer (continued). "For example, a study conducted in Taiwan found that XRCC5 rs3835 was not linked to breast cancer susceptibility, contrasting with the findings of a previous European study." (PMID 33734613, 2021). "Moreover, potential interactions between XRCC5 rs16855458 and alcohol consumption, and between XRCC6 rs2267437 and sleep satisfaction were identified in relation to breast cancer risk." (PMID 33734613, 2021). "Next, we evaluated whether miR-623 had an effect on the expression of XRCC5 in breast cancer cells using western blot analysis." (PMID 32501811, 2020). "Moreover, we proved that miR-623 directly targets XRCC5, which is critical for miR-623-induced proliferation and migration blockage in breast cancer cells." (PMID 32501811, 2020). "Moreover, an antagonistic interaction between XRCC5 rs16855458 and alcohol consumption (pinteraction = 0.017), and a synergistic interaction between XRCC6 rs2267437 and sleep satisfaction were associated with breast cancer risk (pinteraction = 0.0497)." (PMID 33734613, 2021). "In addition, the direct downstream target and regulatory mechanism of XRCC5 on the biological behavior of breast cancer cells remains unknown." (PMID 32501811, 2020). "We have shown that OCT-1 knockdown suppresses the expression of the ARHGDIB, CAPZA2, PHACTR2, CDC42, XRCC5, and CAV1 genes, which is known to be increased in actively metastasizing breast cancer cells." (PMID 36143471, 2022). "(D) Box-plots of HR (BRCA1, BRCA2, ATR) and NHEJ (PRKDC, XRCC5, XRCC6) protein expression levels (ratio to pool) in the different groups of breast cancer cell lines according to AZD1775 response characteristics (recovering-basal, sensitive-basal and recovering-luminal)." (PMID 32628111, 2020).
colon carcinoma (18 papers, 2008 to 2022). "Immunofluorescence assay and co-immunoprecipitation implicated interactions between XRCC5 and p300 in the nucleus of colon cancer cells." (PMID 29049411, 2017). "p300 interacts with XRCC5 by its HAT acetylating XRCC5 in colon cancers and cooperates with XRCC5 to regulate COX-2 expression through acetylating XRCC5 to promote colon cancer growth in vitro and in vivo." (PMID 35269968, 2022). "For example, XRCC5 has been shown to induce cyclooxygenase-2 expression as a complex with p300, thereby promoting colon cancer progression." (PMID 34277436, 2021). "XRCC5 was found to promote the development of numerous cancers, including gastric cancer and colon cancer." (PMID 32258128, 2020). "Our analysis revealed elevated mRNA and protein expression of XRCC6 (Ku70) and XRCC5 (Ku80) in colon cancer compared to normal colon tissue." (PMID 33195430, 2020). "Our recent studies demonstrated a DNA damage-independent interaction between DDB1/DDB2 and XRCC5/XRCC6 in colon cancer cells." (PMID 30410671, 2018). "Targeting the XRCC5/p300/COX-2 signaling pathway is a potentially promising strategy in the treatment of colon cancers." (PMID 29049411, 2017). "In summary, our data proved that XRCC5 promoted tumor cell proliferation via COX-2 in colon cancer cells." (PMID 29049411, 2017). "Knockdown of XRCC5 by siRNAs inhibited the growth of colon cancer cells in vitro and of tumor xenografts in a mouse model in vivo by suppressing COX-2 promoter activity and COX-2 protein expression." (PMID 29049411, 2017). "Immunofluorescence assay and confocal microscopy showed that XRCC5 and p300 proteins were co-located in the nucleus of colon cancer cells." (PMID 29049411, 2017). "Conversely, overexpression of XRCC5 promoted the growth of colon cancer cells by activating COX-2 promoter and increasing COX-2 protein expression." (PMID 29049411, 2017). "In the present study, immunofluorescence assay revealed that both p300 and XRCC5 proteins were co-localized in nuclei of colon cancer cells, co-immunoprecipitation experiment also proved interaction between p300 and XRCC5 in colon cancer cells." (PMID 29049411, 2017). "MTS cell viability assay showed that overexpression of XRCC5 promoted colon cancer cell proliferation, and knockdown of XRCC5 inhibited colon cancer cell proliferation, which suggests that XRCC5 is a proliferation promoting factor in colon cancer cells." (PMID 29049411, 2017). "Conversely, overexpression of XRCC5 promoted growth of colon cancer cells by activating COX-2 promoter and increasing COX-2 protein expression." (PMID 29049411, 2017). "Co-immunoprecipitation assay also proved the interaction between XRCC5 and p300 in nuclear proteins of colon cancer cells." (PMID 29049411, 2017). "p300 cooperates with XRCC5 to regulate COX-2 expression through acetylating XRCC5 to promote colon cancer growth in vitro and in vivo." (PMID 29049411, 2017). "Our study suggests that the XRCC5/p300/COX-2 signaling pathway is a potential target in the treatment of colon cancers." (PMID 29049411, 2017). "These implicate that knockdown of XRCC5 inhibits colon cancer growth in vivo via down-regulating COX-2." (PMID 29049411, 2017). "Other studies reported that XRCC5 promoted colon cancer growth through modulation of COX-2 signalling; potentially associated with the development of systemic lupus erythematosus; and related to hyper proliferation and resistance to apoptosis, genomic instability, and tumorigenesis." (PMID 30897137, 2019). "As p300 contained histone acetyltransferase (HAT) domain, we further hypothesized that p300 acetylated XRCC5 to regulate COX-2 expression in colon cancer cells." (PMID 29049411, 2017). "In this study, we identified XRCC5 as a binding protein of the COX-2 gene promoter in colon cancer cells with streptavidin-agarose pulldown assay and mass spectrometry analysis, and found that XRCC5 promoted colon cancer growth through modulation of COX-2 signaling." (PMID 29049411, 2017).